MCL1 (MCL1 apoptosis regulator, BCL2 family member)
Diseases named in the same sentence as MCL1 in open-access papers (continued):
Sharing a sentence is not in itself a finding about the gene and the disease.
lung carcinoma (continued). "On the other hand, the downregulation of Mcl-1 protein has been found to effectively restore drug sensitivity in cisplatin-resistant lung cancer cells." (PMID 33603033, 2021). "On the other hand, decreased tubulin acetylation by αTAT1 RNA interference downregulated Mcl-1 expression in patient-derived primary lung cancer and paclitaxel-resistant lung cancer cells." (PMID 33824297, 2021). "In order to verify the Mcl-1-targeted activity of the simplified right-half compounds of RT, we first confirmed the Mcl-1-targeted action of RT in primary lung cancer cells." (PMID 32260280, 2020). "Mechanistically, VDAC1 directly interacts with Mcl-1 to regulate the generation of ROS in lung cancer." (PMID 32210729, 2020). "The critical role of MCL-1 in regulating CSC-like property thus provides additional rationale for targeting MCL-1 to treat lung cancer resulting from arsenic and BaP co-exposure." (PMID 32802178, 2020). "We characterized all transcripts whose splicing relies on RNF113A and also established a link between RNF113A and MCL-1 stabilization, with important consequences for the treatment of lung cancer cells showing some acquired resistance to BCL-2 inhibitors." (PMID 32152280, 2020). "Our previous study has verified that nicotine can enhance survival of lung cancer cells through activation of Mcl-1 by phosphorylation." (PMID 31956373, 2020). "In this study, we further confirmed that RT also had anti-cancer activities as well as Mcl-1-targeted activity in patient-derived primary lung cancer cells, with a lower IC50 compared to other first-line chemotherapeutic drugs." (PMID 32260280, 2020). "Taken together, new drugs with modes of action involving eliminating Mcl-1 in lung cancer cells are of interest as candidates for Mcl-1-targeted therapy." (PMID 32260280, 2020). "Having shown the potential Mcl-1 suppression in H460 cells, we next confirmed the Mcl-1- and Bcl-2-targeting activity of TM-(–)-18 and TM-(–)-4a in primary lung cancer cells." (PMID 32260280, 2020). "Our data has some clinical relevance as RNF113A and MCL-1 protein levels positively correlated in clinical cases of lung cancer." (PMID 32152280, 2020). "This suggests that the survival of these lung cancer-cell lines is safeguarded by two or more pro-survival BCL-2 proteins with MCL-1 or BCL-XL being the dominant factor." (PMID 32913197, 2020). "The different ALK-positive lung cancers showed variations in their Bcl-xL and Mcl-1 expression profiles." (PMID 31900393, 2020). "And the present study demonstrates that Mcl-1 is transcriptional regulated by STAT3 pathway induced by nicotine in human lung cancer cells." (PMID 31956373, 2020). "We further analysed the TCGA dataset for LUAD and LUSC in order to specifically understand the role of MCL-1 in lung cancer." (PMID 32913197, 2020). "In particular, increased expressions of Bcl-2 and Mcl-1 reflect a poor prognosis for many malignancies, including lung cancer." (PMID 32260280, 2020). "In summary, our data show that genomic gains of MCL-1 during lung cancer evolution represent a frequent and functionally important survival mechanism for pulmonary adenocarcinoma that represents a rational drug target for the treatment of NSCLC." (PMID 32913197, 2020). "Taken together, these data suggest that whenever MCL-1 is highly expressed it becomes critical for the sustained survival of lung cancer cells." (PMID 32913197, 2020). "It was noteworthy that while we showed in this study that RT reduced both Mcl-1 and Bcl-2 in primary lung cancer cells, RT was previously shown to have a minimal effect on Bcl-2 in H460 cells." (PMID 32260280, 2020). "Mcl-1, an anti-apoptotic member of the Bcl-2 family, was demonstrated to be mainly involved in chemotherapeutic resistance as this protein is frequently found to be highly expressed in lung cancer and the diminishment of Mcl-1 can lead to cancer cell death." (PMID 32260280, 2020).
lung carcinoma (continued). "In lung cancer, evidence from a microarray analysis indicated that Mcl-1 is highly expressed in the cancer tissue of non-small cell lung cancer (NSCLC) patients." (PMID 32260280, 2020). "Genome-wide CRISPRi screens identify factors that resensitize lung cancer cells to inhibition of CDK9 or MCL1." (PMID 31294695, 2019). "Mcl-1 overexpression has been found in several hematological cancers and solid tumors, including chronic myeloid leukemia, gastric cancer and lung cancer." (PMID 31601252, 2019). "The expression level of lncRNA MALAT1 was upregulated in acute myeloid leukemia, and MALAT1 knockdown in lung cancer cells led to upregulation of miR-101-3p expression, and then miR-101-3p reduced myeloid cell leukemia 1 (MCL1) expression by binding to 3’-UTR." (PMID 30925672, 2019). "In lung cancer, evidence has suggested that the myeloid cell leukemia 1 (Mcl-1) protein, an anti-apoptotic member of the Bcl-2 family, is a target for drug action." (PMID 31117253, 2019). "Mcl-1 is an anti-apoptotic protein that has garnered increased attention in lung cancer cell biology as it was shown to be highly expressed in lung cancer." (PMID 31117253, 2019). "In this study, we characterize the MCL-1 inhibitor maritoclax alone or in combination with a BCL-2/xL inhibitor in a panel of lung cancer cell lines." (PMID 31150457, 2019). "Since Mcl-1 is potentially the main contributor to multidrug resistance, this protein is highlighted as a principal target of drug action in the treatment of lung cancer." (PMID 31117253, 2019). "In several cancers, Mcl-1 was frequently found amplified or overexpressed and, in particular, the augmented expression of Mcl-1 reflected the poor prognosis of many malignancies including lung cancer." (PMID 31117253, 2019). "Then, we cloned MCL1 cDNA sequence lacking the 3’-UTR into pcDNA3.1 plasmid (pcDNA3.1-MCL1) and transfected into lung cancer cells to express MCL1 that was insensitive to MALAT1 or miR-101-3p expression." (PMID 29484127, 2018). "Both CCK8 and flow cytometry assays showed that MCL1 knockdown sensitized lung cancer cells to cisplatin by decreasing the IC50 of cisplatin and increasing apoptosis." (PMID 29484127, 2018). "In this study, anoikis sensitizing effect of avicequinone B in human lung cancer cells involved with the down-regulation of caveolin-1 together with the reduction of Mcl-1 and Bcl-2." (PMID 29631569, 2018). "We demonstrated that MALAT1 knockdown leads to miR-101-3p upregulation, which sensitizes lung cancer cells to cisplatin by downregulating MCL1 expression." (PMID 29484127, 2018). "Caveolin-1 was previously shown to play a role in attenuating anoikis response in lung cancer cells by maintain the level of Mcl-1." (PMID 29631569, 2018). "Taken together, these data suggest that miR-101-3p/MALAT1/MCL1 axis is a potential therapeutic target to increase sensitivity of cisplatin-resistant lung cancer cells." (PMID 29484127, 2018). "Previously, caveolin-1 was shown to inhibit anoikis through the preservation of anti-apoptosis Mcl-1 protein in detached lung cancer cells." (PMID 29631569, 2018). "In the same paper, the authors demonstrate extensive mitochondrial fragmentation upon siRNA mediated MCL-1 depletion in H23 lung cancer cells." (PMID 28947954, 2017). "MCL1 is an anti-apoptotic protein involved in resistance to cancer therapies such as cisplatin in lung cancer or rituximab in lymphomas." (PMID 27409838, 2016). "Specifically, miR-101 suppressed tumor progression by targeting MCL-1 in hepatocellular carcinoma and lung cancer." (PMID 26036638, 2015). "We analyzed the expression of the anti-apoptotic proteins Bcl-2, Bcl-xL, and Mcl-1 in different lung cancer cells, and high GCS-expressing cancer cells also showed markedly increased Bcl-xL expression." (PMID 26001295, 2015). "By regulating the expression of MCL-1 and BCL2L2, mir-133b is associated with lung cancer, which was also observed in our results." (PMID 26508990, 2015).
lung carcinoma (continued). "Although treatment with CFZ or CPPD did not significantly modulate Bcl-2 levels in the H1993 or SHP77 cells, future studies should investigate the combined activity of CFZ with Bcl-2 and/or Mcl-1 inhibitors in lung cancer." (PMID 25612802, 2014). "Nicotine-induced Mcl-1 phosphorylation at Thr163 enhances the half-life of Mcl-1, which leads to its long-term survival function and/or chemoresistance of human lung cancer cells." (PMID 24967145, 2014). "We recently discovered that nicotine promotes survival of human lung cancer cells through a novel mechanism by activating the antiapoptotic function of Mcl-1 via its phosphorylation." (PMID 24967145, 2014). "Mcl-1 is a major antiapoptotic member of the Bcl2 family, which is extensively expressed in various human lung cancer cells." (PMID 24967145, 2014). "Accordingly, stimulation of cap-dependent translation by PP2A inhibitor okadaic acid or PP2A knock-down increased levels of c-Myc and Mcl-1 in human lung cancer cells." (PMID 23402580, 2013). "Evidence shows that over-expression of miR-133b also reduces the expressions of both BCL2L2 and MCL-1 and induces apoptosis in lung cancer cell lines." (PMID 24391788, 2013). "API-1 rapidly and potently reduced the levels of Mcl-1 primarily in API-1-senstive lung cancer cell lines." (PMID 24261825, 2013). "In EGFR mutant lung cancer cells, inhibition of PI3K/mTOR and MEK were directly linked to MCL-1 downregulation and BIM upregulation, respectively." (PMID 22808163, 2012). "As for the relationship between human cancer and miR-1, recent articles revealed that miR-1 induced apoptosis through repression of Mcl-1 in lung cancer." (PMID 22068816, 2012). "In our current analysis of colon and lung cancer samples, we demonstrate that Mcl-1 and Bcl-xL are overexpressed and also co-exist in many tumors and that the expression levels of both genes correlate with the clinical staging." (PMID 23171055, 2012). "In this study, we report a significant upregulation of Mcl-1 in lung cancer cell line H1299, the ovarian cancer cell line SKOV3, and the colon cancer cell lines DLD-1, LOVO, SW620 and HCT116 after treatment with different proteasome inhibitors." (PMID 22078414, 2011). "In cancer research fields, ectopic miR-1 induced apoptosis through enhanced activation of caspases 3 and 7, cleavage of their substrate PARP-1, and depletion of antiapoptotic Mcl-1 in lung cancer cells." (PMID 21304530, 2011). "Direct targeting of Mcl-1 by antisense oligonucleotides has already been shown to sensitize the HCC cell line HepG2 as well as lung carcinoma cell lines to cisplatin-induced apoptosis." (PMID 17014711, 2006). "Single-cell transcriptomic profiling of epidermal growth factor receptor (EGFR)-mutant lung cancers reveals tumor-specific upregulation of BCL2L1 alongside downregulation of myeloid cell leukemia 1 (MCL1), a stoichiometric imbalance that buffers apoptotic susceptibility." (PMID 41362736, 2026). "While studying the response of KRAS-mutant lung cancer models to KRASG12C or MEK inhibitors combined with BH3 mimetics, we unexpectedly observed an association between the presence of STK11 mutations and dependence on MCL-1." (PMID 40316540, 2025). "Furthermore, a genome-wide CRISPR inhibition (CRISPRi) screen conducted in lung cancer cells demonstrated that knockout of CUL5, RBX2, or UBE2F (a specific E2 for CRL5 E3s) caused cells to become hypersensitive to a CDK9 inhibitor or MCL-1 inhibitor." (PMID 40699886, 2025). "Overexpressed BCL-2 and MCL-1 have been recognized for various types of lung cancer cells." (PMID 38666017, 2024). "Indeed, Mcl-1 expression in PRKCSH-deficient cells reversed TRAIL resistance, whereas Mcl-1 knockdown increased TRAIL sensitivity in lung cancer cells." (PMID 38200153, 2024). "Additionally, the authors showed effective engagement of the peptides to the Mcl-1 protein, resulting in proteasomal-dependent degradation in a lung cancer cell line overexpressing Mcl-1." (PMID 36662157, 2023).
lung carcinoma (continued). "In addition, MCL1 is involved in anoikis resistance, including in lung carcinoma cells and cutaneous melanoma." (PMID 37446326, 2023). "The pro-survival protein MCL1 is one of the critical components of lung cancer cell survival, and studies have demonstrated the presence of a CMA-mediated MCL1 protein stabilization system in lung cancer cells, which may contribute to cancer progression." (PMID 37509689, 2023). "Also, a recent study demonstrated that Cav‐1 is involved in anoikis resistance in human lung cancer cells through regulation of myeloid cell leukemia 1 (Mcl‐1) by interacting with Mcl‐1 and preventing it from degradation." (PMID 35992829, 2022). "We then investigated the clinical significance of BMI1 and MCL1 in lung cancer patients." (PMID 35794816, 2022). "ABCG1 promotes cell proliferation, migration, and invasion in lung cancer cells, and is associated with expression of anti-apoptotic proteins (B-cell lymphoma 2 (BCL2) or Myeloid-cell leukemia 1 (MCL1), stemness markers (CD133 and ALDH), and proliferative markers (such as c-Myc)." (PMID 34820325, 2021). "In the H1650 lung cancer cell line, the pro-apoptotic Caspase-9, Bak, Puma, and Bax protein levels were elevated, while the anti-apoptotic Bcl-2 levels decreased significantly at unchanged Mcl-1 levels, after methyl-donor treatment." (PMID 33808426, 2021). "MCL1 has also recently been shown to mediate tumor cell migration via binding anion channels on the mitochondrial membrane, resulting in increased production of reactive oxygen species that drive migration in lung cancer." (PMID 34469478, 2021). "Moreover, evidence suggests that the upregulation of another anti-apoptosis protein, Mcl-1 (Myeloid cell leukemia 1) is correlated to the persistence of tumor pathology in lung cancer patients." (PMID 33603033, 2021). "A previous study reported that renieramycin T (RT), a renieramycin-related compound isolated from the blue sponge Xestospongia sp., was dominantly toxic to lung cancer cells and mainly exerted this effect through apoptosis induction via the targeting of Mcl-1 for ubiquitin-proteasomal degradation." (PMID 32260280, 2020). "The up-regulation of survival signals and anti-apoptosis proteins regulating both intrinsic (Bcl-2 and Mcl-1) and extrinsic (c-FLIP) pathway is a phenomenon noted in lung cancer specimens and cell lines, causing high resistance to chemotherapy induced-cell death." (PMID 32069989, 2020). "The present study was performed to determine whether Mcl-1 was mediated by STAT3 signal pathway induced by nicotine in human lung cancer cells." (PMID 31956373, 2020). "Significantly, MARCH5 depletion both abrogated the decrease in MCL1 in response to erlotinib and substantially increased basal MCL1 in multiple prostate, breast, and lung cancer cell lines, indicating that MARCH5 makes a major contribution to regulating basal levels of MCL1." (PMID 32484436, 2020). "Therefore, we examined the STAT3 cascade in nicotine regulation of Mcl-1 transcription in human lung cancer cells." (PMID 31956373, 2020). "While we do not exclude the involvement of these other genes in cancer initiation and/or progression, we hypothesised that the resistance to apoptosis mediated by MCL-1 serves as a critical oncogene addiction in lung cancer and possibly other cancer entities." (PMID 32913197, 2020). "Taken together, these data show that MCL-1 is required for the survival of lung cancer cells." (PMID 32913197, 2020). "The newly identified mechanism suggests that targeting the STAT3 pathway might improve treatment results in some human lung cancer with high levels of Mcl-1." (PMID 31956373, 2020).
lung carcinoma (continued). "However, little is known about the role of MCL-1 during lung cancer clonal evolution and maintenance." (PMID 32913197, 2020). "As RT has been shown to have promising anti-cancer activity against lung cancer through its Mcl-1-targeted activity, as demonstrated in our previous study, we designated RT as a lead compound and generated simplified right-half models in order to elucidate the SAR." (PMID 32260280, 2020). "The Mcl-1, Bcl-2, and proapoptotic Bax in the Bcl-2 family proteins were determined and the results showed that RT significantly decreased the level of Mcl-1 and Bcl-2 in primary lung cancer cells." (PMID 32260280, 2020). "For example, bufalin and ouabain have been shown to downregulate Mcl-1 in lung cancer cells." (PMID 33114727, 2020). "This study is in order to examine whether Mcl-1 is regulated at transcriptional level in human lung cancer cells induced by nicotine." (PMID 31956373, 2020). "Nicotine could activate the antiapoptotic function and enhance the half-life of Mcl-1, which led to its long-term survival function and chemoresistance of human lung cancer cells." (PMID 31956373, 2020). "Therefore, RNF113A promotes chemoresistance to Cisplatin in lung cancer cells, at least by stabilizing MCL-1 levels." (PMID 32152280, 2020). "Degradation of Mcl-1 overcome acquired resistance to osimertinib in EGFR-mutant lung cancer." (PMID 32276600, 2020). "The previous study has demonstrated that nicotine-enhanced survival of lung cancer cells may occur through activation of Mcl-1 by phosphorylation." (PMID 31956373, 2020). "The activation of extrinsic apoptosis evidenced with the reduction of c-FLIP and caspase-8, as well as the modulation of intrinsic apoptosis signaling proteins including Bax and Mcl-1 were observed via Western blot analysis in lung cancer cells cultured with colicin N (10–15 μM) for 12 h." (PMID 32069989, 2020). "Based on our data, patients with lung cancers that exhibit loss of function mutations in either CUL5, RNF7, UBE2F or Elongin B that coincide with high expression of MCL1/Bcl-xL could be good candidates for treatment with CDK9i or MCL1i." (PMID 31294695, 2019). "The reason for the disparate results between lung and endometrial cancer models is unknown but could be due to higher expression of Mcl‐1 in lung cancers and/or differences in other prosurvival/pro‐apoptotic proteins regulated by FGFR1 and FGFR2." (PMID 30537101, 2019). "As lung cancer is the leading cause of cancer mortality and most NSCLC patients develop resistance to first-line treatment, we performed genome-wide CRISPR inhibition (CRISPRi) screens in a NSCLC line resistant to both CDK9 and MCL1 inhibition." (PMID 31294695, 2019). "In an agreement with evidence favoring the use of Mcl-1 targeted therapy, we have shown herein that RT could induce Mcl-1 degradation in lung cancer cells." (PMID 31117253, 2019). "Besides, Mcl-1 was shown to be important for the survival of lung cancer cells and the multivariate analysis indicated MCl-1 expression to be a significant prognostic factor of lung cancer." (PMID 31117253, 2019). "As targeting Mcl-1 for cell degradation has been demonstrated as a promising action of novel anti-cancer drugs, we further evaluated the effect of RT on Mcl-1 stability in lung cancer cells." (PMID 31117253, 2019). "Anti-apoptotic BCL-2 family proteins (BCL-2, BCL-xL, and MCL-1) are emerging as important factors for drug resistance in lung cancer and may represent new targets for treatment." (PMID 31150457, 2019).